ETV1 (ETS variant transcription factor 1)
Diseases named in the same sentence as ETV1 in open-access papers (continued):
Sharing a sentence is not in itself a finding about the gene and the disease.
prostate carcinoma (continued). "Numerous studies have now confirmed that approximately 50% of prostate cancers harbor a recurrent fusion between TMPRSS2 and ERG or ETV1." (PMID 20964841, 2010). "Our panel(s) included probe sets for three members of the ets family involved in prostate cancer; ERG, ETV1, and ETV4, as well as their translocation partner, TMPRSS2." (PMID 18846227, 2008). "We included oligonucleotide probe sets for the three major members of the ets family involved in prostate cancer: ERG, ETV1, and ETV4, as well as their translocation partner TMPRSS2." (PMID 18846227, 2008). "It is possible that like the fusions between TMPRSS2 and ERG, ETV1, ETV4 and ETV5, other functionally identical fusions are involved in changes in gene expression and prostate cancer development but are yet to be discovered." (PMID 18694509, 2008). "Thus, our results suggest that the collective influence of ETV1/ERG and MET signalling can have a significant impact on the trajectory of prostate cancer progression, precipitating its ascent to high‐grade malignancy." (PMID 39374163, 2025). "For example, PXN, which is known as an oncogene in prostate cancer, has higher expression in the ERG and SPOP subtypes of prostate cancer, as compared to normal cells, and lower expression in ETV1 and ETV4 subtypes of prostate cancer, as compared to normal cells." (PMID 36289913, 2022). "Interaction between ETV1, EWS-ERG fusion genes, and EWS-FLI1 fusion genes, members of ETS family transcription factors, and PARP1, a PARPBP-interacting partner has been demonstrated in Ewing sarcoma and prostate cancers." (PMID 35181635, 2022). "Additionally, TMPRSS2-ERG fusions exist in approximately 50% of prostate cancer cases, with TMPRSS2-FEV, -ETV1, -ETV4, and -ETV5 fusions found in other patients." (PMID 34145397, 2021). "Moreover, targeting ETV1 and ERG in prostate cancers significantly reduced invasion and metastasis both in vitro and in vivo." (PMID 33918387, 2021). "Additionally, in prostate cancer, BRD32048 is a new drug used for the treatment of ETV1-positive tumors by directly binding to ETV1 to inhibit its transcriptional activity." (PMID 34736492, 2021). "ETV1, ETV4, and ETV5, which belong to the PEA3 group of genes, are types of ETS transcription factors that are known to promote several types of cancer such as Ewing-like sarcoma, gastric cancer, colorectal cancer, hepatocellular carcinoma and prostate cancer." (PMID 34830169, 2021). "About 50–70% of prostate carcinomas harbor common chromosomal rearrangements fusing one of the ETS transcription family genes (ERG, ETV1, ETV4 or FLI1) with androgen-regulated genes, most commonly TMPRSS2, leading to disruption of androgen receptor signaling via activation of EZH253." (PMID 32873863, 2020). "Additionally, our data show that Twist1 regulates prostate cancer cell invasion and EMT, providing a possible mechanism by which ETV1 mediates prostate cancer cell invasion." (PMID 32296610, 2020). "Similarly, an attempt to show cooperation between ETV1 and JMJD2A, another interaction partner of ETV1, with respective transgenic mice had failed; however, their cooperation in prostate carcinoma formation was revealed in a background of Pten+/− mice." (PMID 31160676, 2019). "Notably, AR and multiple transcription factors extensively reported to be involved in prostate cancer aggressiveness, such as ETV5 and ETV1 were identified as Key TFs with increased transcriptional targets, supporting the biological relevance of our analysis." (PMID 30314329, 2018). "In prostate cancer, many genes from the ETS family participate in fusion transcripts with transmembrane serine protease isoform 2 (TMPRSS2); in fact, three ETS members (ERG, ETV1, and ETV4) contribute to about 80% of TMPRSS2 fusion." (PMID 29455655, 2018).
prostate carcinoma (continued). "Fusion of this gene to members of the ETS family of transcription factors, in particular ERG or ETV1, leads to overexpression of the oncogenes in a large portion of prostate cancer cases, but not in benign prostate samples, in an androgen-dependent manner." (PMID 27285981, 2016). "Using the expression data of our series of prostate carcinomas subtyped for ETS rearrangements, we show that both PC3 and MDA-PCa-2b cells have co-overexpression of ETV1 and ETV4, both ETS in higher levels than those of ERG in VCaP cells, the in vitro model of the TMPRSS2-ERG rearrangement." (PMID 25595908, 2015). "Finally, we show that overexpression of these GRPR targets is restricted to prostate carcinomas harboring ERG and/or ETV1 rearrangements, establishing their potential as therapeutic targets for these particular molecular subsets of the disease." (PMID 26097883, 2015). "Interestingly, the prostate carcinoma cell lines PC3 and MDA-PCa-2b exhibited a remarkable co-expression of the three members of the PEA3 subfamily of ETS transcription factors (ETV1, ETV4 and ETV5)." (PMID 25595908, 2015). "Using the TaqMan Low Density Array (TLDA) technology, we evaluated the expression of the five ETS genes known to be involved in genomic rearrangements in PCa (ERG, ETV1, ETV4, ETV5 and FLI1) in a panel of cell lines representing various subtypes of prostate cancer." (PMID 25595908, 2015). "We selected ETV1 as a possible target of miR-17, due to the fact that its role in melanoma has not been fully elucidated and studies of prostate cancer exhibited that ETV1 affects the migratory ability of the cells." (PMID 26158900, 2015). "Although some prostate cancer cell lines, such as VCaP (ERG) and LNCaP (ETV1) are reported to have oncogenic ETS gene rearrangements, the full extent of oncogenic ETS protein expression, including fusion-independent expression, in commonly used prostate cancer cell lines has not been determined." (PMID 24642271, 2014). "The role of AR in prostate cancer initiation is accentuated by the seminal discovery that the oncogenic ETS family transcription factors, such as ERG and ETV1, are translocated to the loci of androgen regulated genes including TMPRSS2 in approximately 50% of all human prostate cancers." (PMID 24508459, 2014). "In contrast, TDRD1 was not co-expressed with ETV1 (r2 = 0.05) which is an ETS transcription factor found to be sporadically rearranged in prostate cancer." (PMID 23555854, 2013). "To explain the observed co-expression, we employed cellular models of prostate cancer, including cells representing benign (RWPE-1, BPH-1), fusion-negative (PC-3, DU145), ERG-rearranged (VCaP, NCI-H660) and ETV1-rearranged (LNCaP) prostate cancer." (PMID 23555854, 2013). "Gene expression measurements by real-time quantitative PCR revealed a remarkable co-expression of TDRD1 and ERG (r2 = 0.77) but not ETV1 (r2<0.01) in human prostate cancer in vivo." (PMID 23555854, 2013). "Gene fusions found in prostate cancer often involve the ERG, ETV1, or ETV4 gene." (PMID 21789226, 2011). "Because TMPRSS2 is regulated in the prostate by androgens, it was proposed that this gene rearrangement could be a mechanism whereby the ETV1 or ERG oncogenes were overexpressed, leading to prostate cancer." (PMID 18781147, 2008). "Using a novel and powerful bioinformatic technique, they first determined that either ETV1 or ERG (but not both) was commonly overexpressed in prostate cancer cells." (PMID 18781147, 2008). "Although other ETS family members such as ERG comprise recurrent oncogenic gene rearrangements in prostate carcinoma, we did not identify a pattern of expression of other ETS genes that could substitute for the loss of ETV1 function across LNCaP strains." (PMID 40956611, 2025).
prostate carcinoma (continued). "The protein dosage of PEA3 subfamily of ETS transcription factors ETV1, ETV4, and ETV5 is regulated through both transcription and ubiquitylation-mediated protein degradation by E3 ubiquitin ligase COP1, a tumor suppressor in both human prostate cancer and in GEM models of prostate cancer." (PMID 37018402, 2023). "Further, the impact of ETV1 on TGF-β signaling may not be limited to prostate cancer, but pertain to many other normal and diseased tissues where TGF-β exerts important functions during development, homeostasis and pathogenesis." (PMID 31160676, 2019). "Fusion of this gene to members of the ETS family of transcription factors, in particular oncogenes ERG or ETV1, leads to over-expression of these transforming agents in a significant portion of prostate cancers, but not benign prostate tissue, in an androgen-dependent manner." (PMID 29455671, 2018). "The downstream targets of ERG and ETV1 in prostate cancer have not yet been identified." (PMID 27285981, 2016). "We used two prostate cancer cell lines (MDA-PCa-2b and PC3) harboring co-overexpression of ETV1 and ETV4 to gain insight into their biological role in vitro, and found both specific and shared candidate target genes that may play a role in tumor aggressiveness in vivo." (PMID 25595908, 2015). "It has been demonstrated that aberrant expression of ETV1 is not sufficient to initiate neoplastic transformation but instead may cooperate with other genetic events to promote prostate cancer progression." (PMID 24077328, 2013). "Overall, these results suggest that ETV1 and ERG, as well as MET activation, play an important role in prostate cancer cell migration and invasion, without affecting proliferation, and that MET receptor activation leads to an increase in these responses and MET repression to reversion." (PMID 39374163, 2025). "Thus, separately, ETV1, ERG and MET are well known to induce tumour properties in different cancers but their concomitant activity in prostate cancer is not yet described." (PMID 39374163, 2025). "Despite the fact that mutual exclusivity of ETS rearrangements is the rule (at least at the cellular level) in prostate carcinomas and the impact on cell invasion shared by ERG and ETV1, ETS members show both lack of tissue specificity and co-expression within a tissue." (PMID 25595908, 2015). "However, the biological role of ETS fusions in prostate cancer development is still controversial, since ERG and ETV1 by themselves, do not seem to be tumorigenic." (PMID 21829708, 2011).
Ewing sarcoma (27 papers, 2011 to 2025). A small round cell tumor that lacks morphologic, immunohistochemical, and electron microscopic evidence of neuroectodermal differentiation. "Ewing's sarcomas result from chromosomal translocations that generate dominant transforming fusion proteins of the transactivation domain of the EWS protein with the ETS domain of one of the five Ets proteins Etv1, Etv4, Erg, Fli1, and Fev (Fifth Ewing Variant, PET-1)." (PMID 25866208, 2015). "At the same time, YK-4-279 has been shown to inhibit ERG and ETV1 transcription in prostate cancer cells, therefore, it might also be active against Ewing sarcoma cells with commonly and less commonly presented fusion in the tumors with Ewing sarcoma." (PMID 35454895, 2022). "It was later reported that Ewing sarcoma has more chromosomal translocations, including EWS/FLI fusion, EWS/ERG fusion, EWS/FEV fusion, EWS/ETV1 fusion, EWS/ETV4 fusion, FUS/ERG fusion, FUS/FEV fusion, and FUS/ETV4 fusion." (PMID 36964542, 2023). "3,3′-Diindolylmethane was effective in reducing ETV1 and ETV4 transcripts, with both shown to promote Ewing’s sarcoma." (PMID 33918387, 2021). "For example, Ewing sarcoma translocations involve one of five closely homologous ETS family members (FLI, ERG, FEV, ETV1, and ETV4)." (PMID 34145397, 2021). "The ERG related members include ETV1, ETV4, ETV5 and FLI1 which have been shown to overexpress in different diseases including CaP, Ewing sarcoma, and acute myeloid leukemia." (PMID 28191285, 2016). "Ewing sarcoma tumouroids preserved characteristic EWSR1 rearrangements with erythroblast transformation-specific (ETS) family of transcription factors such as FLI1, ERG and ETV1." (PMID 41034452, 2025). "Other fusion partners seen with Ewing sarcoma include FEV, ETV1, and ETV4." (PMID 40255709, 2025). "Indeed BRD32048 directly binds ETV1, a member of the ETS transcription factor family translocated in prostate cancer and Ewing sarcoma, and inhibits its transcriptional activity on MMP1 promoter." (PMID 29921764, 2018). "Alternatively, EWSR1 can be fused with ERG, ETV1, E1A-F (alias ETV4) or FEV in Ewing sarcoma." (PMID 29416716, 2018). "Most Ewing sarcomas harbor gene fusions involving the FLI1, ERG, ETV1, ETV4, or FEV gene." (PMID 21789226, 2011). "Moreover, in Ewing sarcoma tumors, the EWS gene might be translocated onto the ETV1 gene and the fusion protein exerts oncogenic properties." (PMID 26158900, 2015). "Ewing Sarcoma (ES) is a primitive small round cell sarcoma defined by fusions involving members of the FET (predominantly EWSR1 or FUS) and ETS (most commonly including FLI1, ERG, ETV1, ETV4, or FEV) gene families." (PMID 35059992, 2022).
gastrointestinal stromal tumor (19 papers, 2012 to 2025). "The overexpression of ETV1 in gastrointestinal stromal tumors can increase the expression of anti-apoptotic proteins, Bcl-2, and decrease the expression of pro-apoptotic proteins, Bax, thereby inhibiting tumor cell apoptosis." (PMID 34736492, 2021). "It has been reported that a gastrointestinal stromal tumor arising from ICC shows high expression levels of c-Kit through the stabilization of ETV1, which results in an acceleration of tumor growth." (PMID 31596858, 2019). "There has even been a novel transcription factor ETV1 identified, which is unique to gastrointestinal stromal tumors (GISTs), suggesting that KCTD10 functions as a tumor suppressor protein." (PMID 31583032, 2019). "One such mechanism that decreases protein degradation of the Ets family member, ETV1, has been described in gastrointestinal stromal tumors." (PMID 22860005, 2012). "Accumulating evidence has highlighted the crucial role of ETV1 in gastrointestinal stromal tumors." (PMID 40894482, 2025). "In addition, ETV1 is also known to be required for gastrointestinal stromal tumor initiation and proliferation." (PMID 36109787, 2022). "It was demonstrated in gastrointestinal stromal tumors that ETV1 is a target of miR-17." (PMID 26158900, 2015). "This is because, as an ETS family transcription factor, the focus on ETV1 has been on ETS-dependent tumours, especially for the development of gastrointestinal stromal tumours." (PMID 28203258, 2017). "For example, ERG, ETV1, and ETV4 can be upregulated in prostrate cancers, and ETV1 is upregulated in post gastrointestinal stromal tumors and in more than 40% of melanomas." (PMID 26683696, 2015). "Interestingly, it also can function as a tumor suppressor-miR in other cancer types, for example, in erythroblastic leukemia, and gastrointestinal stromal tumors, miR-222 inhibits cell growth and induces apoptosis by targeting KIT and ETV1." (PMID 27811362, 2016).
melanoma (19 papers, 2014 to 2025). A malignant, usually aggressive tumor composed of atypical, neoplastic melanocytes. "We found that patient mutations in COP1 or DET1 inactivated CRL4COP1/DET1 in melanoma cells, stabilized ETV1, ETV4, and ETV5, and conferred resistance to inhibitors of the MAPK pathway." (PMID 40643496, 2025). "Whole-genome sequencing in melanoma revealed six distinct re-arrangements involving breakpoints within the ETV1 introns, which are associated with ETV1 amplification." (PMID 26158900, 2015). "COP1 loss in A375 melanoma and GIST-T1 cell line-derived xenograft models led to increased ETV1 (and ETV4/5) levels and resistance to MAPK inhibitor treatments." (PMID 34066106, 2021). "Two studies also observed that 5.3–18% of melanoma patients exhibited an increase in ETV1 expression." (PMID 33424867, 2020). "An early study also observes that overexpression of ETV1 confers resistance to MAPK inhibitors in BRAF-mutant melanoma." (PMID 33424867, 2020). "It has been confirmed that miR-17-5p can function as an oncogene or tumour suppressor by targeting ETV1 in melanoma or GIST." (PMID 29126392, 2017). "miR-17-5p degrades ETV1 expression at the protein level in melanoma cells, and at the mRNA level in GIST cells." (PMID 29126392, 2017). "Remarkably, ETV1 overexpression substantially decreased the motility of both WM-266-4 and 624mel melanoma cell lines by 40% and 57% respectively, as compared to the control cells." (PMID 26158900, 2015). "Further, in both melanoma cell lines ETV1 knockdown by selective siRNA successfully pheno-copies the facilitated cell migration, while overexpression of ETV1 inhibits cell motility and migration." (PMID 26158900, 2015). "Remarkably, knockdown of ETV1 significantly enhanced the migratory ability of both WM-266-4 and 624mel melanoma cell lines, as compared to the control cells." (PMID 26158900, 2015). "In this study, we demonstrate new evidence that miR-17 induces melanoma cell motility and migration by targeting directly the ETV1 protein at the protein translation level." (PMID 26158900, 2015). "Two cell lines with focal ETV1 amplification demonstrated ETV1 dependency in melanoma proliferation, and ETV1 co-expression with oncogenic mutant NRAS or BRAF demonstrated enhanced proliferation." (PMID 26158900, 2015). "Here we demonstrate that ETV1 inhibits melanoma cell migration, and further define miR-17 as a direct regulator of ETV1 expression at the protein translation level." (PMID 26158900, 2015). "Worth noting, the majority of melanomas in fact lack ETV1 amplification, representing > 80% of the cases." (PMID 26158900, 2015). "We show that ETV1 inhibits melanoma cell motility and migration and functions as a tumor suppressor." (PMID 26158900, 2015). "Highly expressed miR-17 enhances melanoma cell motility and migration by repressing translation of the ETV1 protein, which may support the development of metastasis." (PMID 29126392, 2017). "Indeed, ETV1 overexpression significantly inhibited the migratory ability of both WM-266-4 and 624mel melanoma cell lines by 58% and 22% respectively, as compared to the control cells." (PMID 26158900, 2015). "Our combined results therefore suggest that ETV1 has a suppressive role in melanoma." (PMID 26158900, 2015). "A recent study showed a small subset of melanomas (5.3%), which over-expresses ETV1." (PMID 26158900, 2015). "The current knowledge about the role of ETV1 and mechanism in melanoma is very limited." (PMID 26158900, 2015). "In conclusion, we show a new role for miR-17 in melanoma, facilitating cell motility, by targeting the translation of ETV1 protein, which may support the development of metastasis." (PMID 26158900, 2015). "Another report suggested that ETV1 may play a role in melanocyte transformation and melanoma-genesis and has identified copy gains of ETV1 gene present in 13% of primary and 18% of metastatic melanomas." (PMID 26158900, 2015).